PA2G4 (proliferation-associated 2G4)
Description:
May play a role in a ERBB3-regulated signal transduction pathway. Seems be involved in growth regulation. Acts a corepressor of the androgen receptor (AR) and is regulated by the ERBB3 ligand neuregulin-1/heregulin (HRG). Inhibits transcription of some E2F1-regulated promoters, probably by recruiting histone acetylase (HAT) activity. Binds RNA. Associates with 28S, 18S and 5.8S mature rRNAs, several rRNA precursors and probably U3 small nucleolar RNA. May be involved in regulation of intermediate and late steps of rRNA processing. May be involved in ribosome assembly. Mediates cap-independent translation of specific viral IRESs (internal ribosomal entry site) (By similarity). Regulates cell proliferation, differentiation, and survival. Isoform 1 suppresses apoptosis whereas isoform 2 promotes cell differentiation (By similarity).
Synonyms: hG4-1; EBP1; ITAF45; p38-2G4
Tractability: Small molecule: a structure with a bound ligand is known; it has a high-quality binding pocket. Antibody: its Gene Ontology location is reachable by antibodies, with high confidence. PROTAC: UniProt records ubiquitination sites on it; ubiquitination databases record sites on it; its protein half-life has been measured.
Gene: Protein-coding gene on chromosome 12 (56,104,349 to 56,116,329, forward strand). Ensembl gene ENSG00000170515.
Subcellular location: Cytoplasm (Isoform 1); Nucleus, nucleolus; Cytoplasm (Isoform 2)
Subcellular location (Human Protein Atlas): Cytosol
Pathways (Reactome):
Immune System: Neutrophil degranulation
Gene Ontology:
Molecular function: nucleic acid binding; protein binding; RNA binding; transcription corepressor activity; ubiquitin protein ligase binding
Biological process: negative regulation of DNA-templated transcription; negative regulation of apoptotic process; positive regulation of cell differentiation
Cellular component: cytoplasm; cytosol; extracellular exosome; membrane; nucleolus; nucleus; azurophil granule lumen; extracellular region
Genetic constraint (gnomAD): Loss-of-function variants: 4 observed, 39.7 expected, observed/expected ratio (o/e) 0.1, 90% interval 0.049 to 0.23. The upper end of that interval is the gene's LOEUF score, 0.23, which puts it in group 1 of 6, group 1 being the genes least tolerant of losing a copy. Missense variants: 161 observed, 408.71 expected, observed/expected ratio (o/e) 0.39, 90% interval 0.35 to 0.45. Synonymous variants: 122 observed, 141.38 expected, observed/expected ratio (o/e) 0.86, 90% interval 0.74 to 1.
Homologues: Orthologues: chimpanzee PA2G4 (100% identical), dog PA2G4 (99% identical), rabbit PA2G4 (99% identical), mouse Pa2g4 (99% identical), rat Pa2g4 (99% identical), guinea pig PA2G4 (99% identical), tropical clawed frog pa2g4 (87% identical), zebrafish pa2g4a (84% identical), rat AABR07065265.1 (61% identical), Caenorhabditis elegans map-2 (22% identical), Drosophila melanogaster und (19% identical), Caenorhabditis elegans app-1 (11% identical), and 1 more. Paralogues in human: METAP2 (22% identical), XPNPEP2 (14% identical), PEPD (13% identical), METAP1D (13% identical), XPNPEP1 (12% identical), METAP1 (12% identical), XPNPEP3 (11% identical).
Diseases named in the same sentence as PA2G4 in open-access papers:
PA2G4 is named in the same sentence as 37 diseases in open-access papers, as found by Europe PMC text mining. Sharing a sentence is not in itself a finding about the gene and the disease. The quoted sentences say what the papers report.
gallbladder cancer (6 papers, 2019 to 2023). "For example, circERBB2 promotes gallbladder cancer progression by regulating PA2G4‐modulated ribosomal DNA transcription." (PMID 36606322, 2023). "In gallbladder cancer progression, researchers also showed that a circRNA generated from the oncogene ERBB2, named as circERBB2 promotes gallbladder cancer progression by regulating PA2G4-dependent rDNA transcription." (PMID 34489401, 2021). "circERBB2, containing exons 3 to 7 of ERBB2, bound and promoted nucleolus localization of PA2G4, a modulator of ribosomal DNA (rDNA) transcription, to form a circERBB2-PA2G4-TIFIA complex and increase Pol I activity and rDNA transcription in gallbladder cancer." (PMID 33537235, 2020).
breast carcinoma (5 papers, 2010 to 2022). "Six of the 11 non-mitosis related genes were previously associated with poor survival in breast cancer patients: KRT17, MMP12, SLC7A5, SQLE, GABRP and PA2G4, but the remaining 5 had not been previously associated with cancer risk: CCDC86, NUP107, NUTF2, WASF1 and ELOVL6." (PMID 23077491, 2012). "Moreover, PA2G4 overexpression induces differentiation of human breast cancer cells, inhibits proliferation of human fibroblasts, and suppresses growth and metastasis of salivary adenoid cystic carcinoma cells." (PMID 20421926, 2010).
prostate carcinoma (5 papers, 2019 to 2023). A carcinoma that arises from epithelial cells of the prostate gland. "A progressive increase in the expression of GNL3 and PA2G4 was observed during cancer progression having significant association with poor survival in prostate cancer patients." (PMID 37345060, 2023). "Based on the published information and our bioinformatics approach, we propose GNL3 and PA2G4 as prognostic biomarkers in prostate cancer." (PMID 37345060, 2023). "We found that the higher expression of GNL3, CHCHD8, PA2G4, and RRP9 genes with HR more than 1.0 was closely associated with poor overall survival and disease-free survival in prostate cancer patients." (PMID 37345060, 2023). "GNL3 and PA2G4 have been found to be overexpressed in several human cancers, including prostate cancer." (PMID 37345060, 2023). "This review article mainly highlights the function of GNL3 and PA2G4 and focuses on the opportunities for their development as prognostic biomarkers in prostate cancer." (PMID 37345060, 2023). "Using a bioinformatics approach, we predicted GNL3 and PA2G4 as biomarkers of prognostic significance in prostate cancer." (PMID 37345060, 2023). "We found that GNL3 and PA2G4 showed comparatively significant and better performance in prostate cancer specimens compared to normal samples." (PMID 37345060, 2023). "Overall, our analysis predicted GNL3 and PA2G4 as prognostic biomarkers of clinical significance in prostate cancer." (PMID 37345060, 2023). "In prostate cancer, PA2G4 was found to downregulate the expression of androgen receptor (AR) and AR-regulated genes, leading to lower incidence and weight of LNcaP tumors." (PMID 35526051, 2022). "Based on our analysis, GNL3 and PA2G4 showed better performance as prognostic biomarkers and may be used separately or in combination in prostate cancer." (PMID 37345060, 2023). "Clinical data suggest that GNL3 and PA2G4 could be developed as prognostic biomarkers of clinical significance in prostate cancer." (PMID 37345060, 2023). "We have also included PA2G4 which acts as an androgen receptor corepressor and may be downregulated in prostate cancer." (PMID 32630458, 2020). "The PA2G4 gene encodes proliferation-associated protein 2G4, also known as ErbB3-binding protein 1 (EBP1), which plays a role in cell signal transduction, transcription, and translation and has been shown to suppress growth in certain cancers, including breast and prostate cancers (66, –, 72)." (PMID 30723129, 2019). "The GNL3, CHCHD8, PA2G4, and RRP9 genes were selected to predict their ability in overall and disease-free survival in prostate cancer patients." (PMID 37345060, 2023). "Based on the information CHCHD8, GNL3, PA2G4, and RRP9 genes were selected to further explore the prognostic significance in prostate cancer." (PMID 37345060, 2023). "In prostate cancer, aberrant expression of GNL3 and PA2G4 correlate with tumorigenesis and metastasis." (PMID 37345060, 2023). "In our differential expression analysis, we found that CHCHD8, GNL3, PA2G4, and RRP9 have 27.0-, 38.6-, 12.8-, and 7.6-times higher expression in prostate cancer specimens in comparison to normal prostate tissue." (PMID 37345060, 2023). "We have not proved the importance of PA2G4 and Ki67 for CaP detection as they weakly correlated with some prostate cancer-related markers (e.g., AMACR), but also with leukocyte-specific CD45 and house-keeping genes (TBP and RHOA)." (PMID 32630458, 2020).
acute myeloid leukemia (3 papers, 2021 to 2025). Acute myeloid leukemia (AML) is a group of neoplasms arising from precursor cells committed to the myeloid cell-line differentiation. "Knockdown of LINC00987 suppresses acute myeloid leukemia progression by inhibiting the IGF2BP2‐mediated PA2G4 expression." (PMID 36606322, 2023).
cervical cancer (3 papers, 2017 to 2023). A primary or metastatic malignant neoplasm involving the cervix. "PA2G4 has also been shown to be highly expressed in a variety of cancers, including cervical cancer, CRC, nasopharyngeal carcinoma and salivary carcinoma." (PMID 37604903, 2023). "We found that HPV E6/E7-related master regulators (ENO1, FOSB, PA2G4, SOX9, TEAD4, FOXO4, and MNT) were significantly differently expressed (p < 0.001) in the cervical cancer TCGA samples (n = 306) than in normal cervix (n = 11) tissue." (PMID 28670312, 2017). "The following genes ENO1, FOSB, PA2G4, SOX9, and TEAD4 were highly expressed in cervical cancer in comparison to normal cervix (p < 0.001), while FOXO4 and MNT were significantly lower in cervical cancer (p < 0.001)." (PMID 28670312, 2017).
hepatocellular carcinoma (3 papers, 2021 to 2023). A malignant tumor that arises from hepatocytes. "These analyses suggest that EFTUD2, GAPDH, NOP56, and PA2G4 were potential biomarkers for the diagnosis and prognosis of hepatocellular carcinoma." (PMID 34257558, 2021).
neuroblastoma (3 papers, 2023 to 2025). Neuroblastoma (NB) is the most common solid, extracranial childhood tumor. "Proliferation-associated protein 2G4 (PA2G4) directly binds to and stabilizes MYCN protein, leading to markedly increased MYCN levels in neuroblastoma cells." (PMID 41002386, 2025). "In neuroblastoma cells, PA2G4 and MYCN act together in a forward feedback loop, driving continued tumorigenesis." (PMID 41002386, 2025). "We previously demonstrated that pharmacological inhibition of the PA2G4-MYCN protein interaction using the small molecule WS6 exerts anti-tumorigenic effects in neuroblastoma models." (PMID 41002386, 2025). "While the PA2G4-MYCN interaction in neuroblastoma has been well characterized, little is known about its potential role in regulating c-MYC." (PMID 41002386, 2025). "In vitro, PA2G4 knockout partially reduced cell viability in neuroblastoma cell lines, with effects observed in MYCN-dependent and -independent contexts." (PMID 41002386, 2025). "To determine the importance of PA2G4 to MYCN-driven neuroblastoma in vivo, we created Th-MYCN transgenic mice harboring a deletion of the PA2G4 gene." (PMID 41002386, 2025). "We present the first in vivo evidence demonstrating the essential role of PA2G4 in MYCN-driven neuroblastoma." (PMID 41002386, 2025). "To investigate the functional importance of PA2G4 in MYCN-driven neuroblastoma in vivo, we utilized the Th-MYCN transgenic mouse model, in which the human MYCN gene is expressed under the control of the tyrosine hydroxylase promoter." (PMID 41002386, 2025). "Real-time PCR analysis showed that c-MYC knockdown resulted in a significant (p < 0.01) decrease in PA2G4 mRNA expression compared to the control after 48 h in neuroblastoma cells, suggesting that c-MYC plays a role in PA2G4 transcriptional regulation." (PMID 41002386, 2025). "WS6 analogues also inhibited the malignant neuroblastoma cell phenotype in vitro; their cytotoxicity was partially dependent on PA2G4 and MYCN protein expression." (PMID 36980710, 2023). "WS6, a chemical inhibitor of PA2G4, disrupted the PA2G4-MYCN binding in neuroblastoma cells with significant antitumour effects in vitro and in vivo." (PMID 36980710, 2023). "The purpose of this study is to characterise and evaluate our novel WS6 analogous as inhibitors of MYCN and PA2G4 oncogenic functions in neuroblastoma." (PMID 36980710, 2023). "A small molecule known to bind PA2G4, WS6, significantly decreased tumorigenicity in TH-MYCN neuroblastoma mice, along with the inhibition of PA2G4 and MYCN interactions." (PMID 36980710, 2023). "The WS6 analogues inhibited neuroblastoma cell phenotype in vitro, in part through effects on apoptosis, while their anti-cancer effects required both PA2G4 and MYCN expression." (PMID 36980710, 2023). "Taken together with prior studies, our findings in neuroblastoma highlight PA2G4 as a conserved and functionally significant MYC regulatory factor which may have a role in many c-MYC-driven malignancies." (PMID 41002386, 2025). "Here, we demonstrate that PA2G4 is essential for MYCN-driven tumor growth in neuroblastoma in vivo." (PMID 41002386, 2025). "This leaves open the possibility that in MYC-driven neuroblastoma, PA2G4 could also play a role, though further datasets will be needed to clarify this." (PMID 41002386, 2025). "Moreover, PA2G4 elevates c-MYC protein levels in neuroblastoma cells by inhibiting its ubiquitin-mediated degradation." (PMID 41002386, 2025). "In neuroblastoma cells, PA2G4 is a transactivation target for MYCN." (PMID 36980710, 2023). "Two of our hit compounds, #5333 (also called SVI-5333) and #5338 (also called SVI-5338), had a significantly increased therapeutic window compared to WS6 and inhibited the malignant phenotype of neuroblastoma cells in vitro, which partly depended on PA2G4 and MYCN expression." (PMID 36980710, 2023).
neuroblastoma (continued). "Targeting PA2G4/MYCN binding by WS6, a small molecule inhibitor, leads to reduced levels of both proteins and suppresses neuroblastoma tumorigenicity in vitro and in vivo." (PMID 41002386, 2025). "We have previously identified PA2G4 as a direct protein-binding partner of MYCN and drive neuroblastoma tumorigenesis." (PMID 36980710, 2023). "By disrupting the PA2G4-MYCN interaction, treatment with WS6 increased MYCN degradation, in turn decreasing overall levels of MYCN and PA2G4 protein in neuroblastoma cells." (PMID 36980710, 2023). "Inhibition of PA2G4 and MYCN binding by WS6 can reduce levels of both proteins and neuroblastoma tumorigenicity in vitro and in vivo." (PMID 36980710, 2023). "Together, these results showed that PA2G4 was required for c-MYC protein stability in these neuroblastoma cell lines, independent of transcriptional regulation." (PMID 41002386, 2025). "In this study, we reveal PA2G4 as a critical cofactor for both MYCN and c-MYC in neuroblastoma." (PMID 41002386, 2025). "Next, we examined whether #5333 and #5338 treatment for 48 h affected the levels of WS6 target proteins, PA2G4, and MYCN in neuroblastoma cells." (PMID 36980710, 2023).
colon cancer (2 papers, 2010 to 2022). "In colon cancer, PA2G4 was found to enhance rRNA synthesis by facilitating the function of TIF-90 and preventing its proteasomal degradation, further promoting cancer cell proliferation, colony formation, invasion and resistance to radiosensitivity." (PMID 35526051, 2022). "PA2G4 was found to be highly expressed in cervical cancer, colon cancer, nasopharyngeal carcinoma and salivary adenoid cystic carcinoma, while it was found to be downregulated in HER2+ breast cancer and bladder cancer." (PMID 35526051, 2022). "The regulation of 14-3-3ε, 14-3-3τ, 14-3-3ζ and PA2G4 by Snail1 was reproduced in HT29 colon cancer cells." (PMID 20421926, 2010). "The repression of 14-3-3ε, 14-3-3τ, 14-3-3ζ and PA2G4 by Snail1 in nuclear extracts was reproduced in two independent experiments in another human colon cancer cell line, HT29." (PMID 20421926, 2010). "We found that Snail1 represses also PA2G4 expression in human colon cancer cells." (PMID 20421926, 2010).
ischemic stroke (2 papers, 2022 to 2025). A stroke disorder caused by obstruction of blood flow to the brain, due to thrombotic (local blood clot formation) or embolic (due to a blood clot or other material traveling from another site) event. "GWAS also showed that variants in CDKN1A are associated with ischemic strokes, atrial fibrillation and cardioembolic stroke, while variants in other experimentally validated gene targets of mir-423-3p; PA2G4 are associated with BMI and BCL2L11 with T2DM and cholesterol levels." (PMID 36277770, 2022).
leukemia (2 papers, 2024 to 2025). A malignant (clonal) hematologic disorder, involving hematopoietic stem cells and characterized by the presence of primitive or atypical myeloid or lymphoid cells in the bone marrow and the blood. "PA2G4 overexpression rescues AML cells from the inhibitory effects of HDACis, while genetic and small molecule inhibition of PA2G4 abrogates EVI1 in 3q26 AML cells, including in patient-derived leukemia xenografts." (PMID 38834613, 2024). "Taken together, our data suggest that PA2G4 bridges EVI1 to MYC and supports the disruption of this protein to diminish their respective oncogenic signals in this leukemia subtype." (PMID 38834613, 2024).
viral infection (2 papers, 2011 to 2025). "Down regulation of anti-proliferative factors like PHB and gain in proliferation associated factor PA2G4 may be part of cellular countercurrents of signaling in the situation of stress caused by virus infection." (PMID 21533140, 2011).
Burkitt lymphoma (1 paper, 2025). A rare form of malignant mature B-cell non-Hodgkin lymphoma. "Knockdown of c-MYC following the addition of Doxycycline (Dox) to the murine Burkitt lymphoma cell line, P493-6, in vitro also led to a significant (p < 0.05) decrease in c-MYC and PA2G4 protein expression over 96 h." (PMID 41002386, 2025).
cervical tumor (1 paper, 2017). "According to the available data in the Human Protein Atlas, most of tested cervical tumor samples were positive for protein expression of EGR3, NR4A2, SOX9, PA2G4, ENO1, and TEAD4." (PMID 28670312, 2017).
epilepsy (1 paper, 2021). A brain disorder characterized by episodes of abnormally increased neuronal discharge resulting in transient episodes of sensory or motor neurological dysfunction, or psychic dysfunction. "Herein, we identified seven genes (NCL, SEPHS2, PA2G4, SLC35G2, MYO1C, GPR158, and POU3F1) with de novo variants but unknown pathogenicity that were not previously associated with epilepsy." (PMID 34489640, 2021).
glaucoma (1 paper, 2022). Increased pressure in the eyeball due to obstruction of the outflow of aqueous humor. "Reduced expression of PA2G4 has been observed in aging retina with glaucoma." (PMID 35806375, 2022).
glioblastoma (1 paper, 2025). The most malignant astrocytic tumor (WHO grade IV). "Overexpression of PA2G4 has been associated with enhanced tumor progression in glioblastoma and oral squamous cell carcinoma pre-clinical models, supporting its role as a driver of malignancy." (PMID 41002386, 2025).
liver cancer (1 paper, 2022). An epithelial or non-epithelial malignant neoplasm that arises from the liver. "In our research, PA2G4 was found to promote EMT of liver cancer cells by stabilizing mRNA of FYN in a YTHDF2 dependent manner, and was an independent risk factor for recurrence." (PMID 35526051, 2022).
lung carcinoma (1 paper, 2021). "Candidate genes ACTR3, ARPC5, and HNRNPK were highly expressed in almost all types of lung cancer immune cells, while RAB13, PA2G4, and WDR12 were found to be less abundant in the majority of myeloid populations in lung cancer." (PMID 34868230, 2021).
myopia (1 paper, 2018). "Moreover, it points out that multiple associated ribosomal deficits might play a role in DBA-related phenotypes, considering the simultaneous deletion of three of them in the index case (RPS26, PA2G4 and RPL41), and it confirms the association among SLC39A5 functional disruption and severe myopia." (PMID 30524470, 2018).
thyroid cancer (1 paper, 2022). "In thyroid cancer cells, PA2G4 inhibited proliferation, migration and invasion by increasing the expression of RAS protein activator like 1 (RASAL1)." (PMID 35526051, 2022).